SOD3 (superoxide dismutase 3)
Diseases named in the same sentence as SOD3 in open-access papers (continued):
Sharing a sentence is not in itself a finding about the gene and the disease.
infection (22 papers, 2011 to 2025). The state of being infected such as from the introduction of a foreign agent such as serum, vaccine, antigenic substance or organism. "Among the 88 total secreted proteins under positive selection, seven were found to be significantly differentially upregulated during a mouse model of infection in Blastomyces, including a high-affinity nickel transporter (PADG_05345), an oxidoreductase (PADG_00948) and the SOD3-encoded protein." (PMID 27704050, 2016). "Compared with the blank group, the mRNA levels of SOD1, SOD2, and SOD3 were significantly increased on the fifth day after PR8 infection." (PMID 36829913, 2023). "By 8 days post-infection, when SOD3(+) fungal burdens are approaching their maximal level, thick collars of inflammatory cells (primarily macrophages and lymphocytes with fewer neutrophils) surround most blood vessels and/or bronchioles." (PMID 22615571, 2012). "To explore the role of Sod3 in this interaction, we measured the survival of Histoplasma yeast cells following infection of both resting and activated macrophages." (PMID 22615571, 2012). "80% and 93% of SOD3(+) yeast cells remain viable after infection of resting macrophages at 2 and 4 hours." (PMID 22615571, 2012). "At 4 days post-infection, lesions are more pronounced in lungs infected with SOD3(+) yeasts than with sod3Δ yeasts." (PMID 22615571, 2012). "Previous work in our laboratory demonstrated that C. elegans releases significant amounts of ROS during infection and that expression of oxidative stress response genes such as sod-3 is induced." (PMID 22216003, 2011). "Infection status drove significant increases for genes except Sod3 (p ≤ 0.04)." (PMID 35312688, 2022). "Mutants defective in the cell signaling or other defense molecules of C. elegans were either more susceptible (defective in nsy-1, sek-1, pmk-1, ced-3, ced-9, skn-1, or daf-16) or more resistant (defective in age-1 or dbl-1) to DT104 infection than the WT except for the mutant defective in sod-3." (PMID 33763087, 2021). "This implies that SOD3 may have a role in protecting against infection, and arginine at amino acid 213 in the HBD plays a key role in this function." (PMID 32004354, 2020). "In addition, in Blastomyces it has been also shown the up-regulation of SOD3 during the interaction with macrophages and in a mouse model of infection." (PMID 26963091, 2016). "Thus, the protective effects of Sod3 are required for Histoplasma to establish both lethal and sublethal infections in vivo." (PMID 22615571, 2012). "Pathogenicity might affect sod-3 abundance through regulation of the insulin-like signaling pathway because this pathway mediates response to pathogen infection." (PMID 21533182, 2011). "Furthermore, SOD3 is expressed during in vivo infection consistent with a role in virulence." (PMID 22615571, 2012). "Thus, Sod3 is an essential virulence factor that protects Histoplasma yeasts from killing by ROS produced by the host, particularly during the innate immune response to infection." (PMID 22615571, 2012). "When infection with ETEC the expression of almost all selected genes was upregulated (P ≤ 0.05) except for tir-1, clec-60, skn-1, and sod-3." (PMID 30250464, 2018). "Sod1−/− but not Sod2+/− or Sod3−/− mice lost more body weight compared to WT mice, which started in the early phase of infection." (PMID 26588782, 2015). "Consistent with this early involvement of ROS, yeasts lacking Sod3 function are rapidly killed during the early phases of infection." (PMID 22615571, 2012). "Nevertheless, SOD3 and SOD4 were induced more than 4-fold in yeast encountering intact neutrophils at one or more time points, but not in the hypha infection." (PMID 28874114, 2017). "Again, Sod1−/− mice, but neither Sod2+/− nor Sod3−/− mice, showed highly elevated concentrations of ALT within the first 2 days of infection." (PMID 26588782, 2015).
infection (continued). "However, pretreatment with LB1 significantly increased (P ≤ 0.05) the life-span of the mutants that are defective in sod-3, skn-1, or dbl-1 and showed no change, decreased or increased resistance to DT104 infection in the previous assay without LB1 pretreatment, respectively." (PMID 33763087, 2021).
cardiovascular disease (6 papers, 2010 to 2025). "This variant also decreases SOD3 abundance in tissues, resulting in deleterious effects in cardiovascular diseases, revealing the importance of regulating the proteolytic removal of the HBD in protection against extracellular oxidative damage throughout the body." (PMID 41502422, 2025). "Our ongoing investigation will explore the regulatory nature of SOD3 acetylation in murine models of hepatic and cardiovascular disease." (PMID 41502422, 2025). "SOD3 is expressed in most tissues and is considered the major enzymatic antioxidant defense against vascular and cardiovascular diseases." (PMID 38539811, 2024).
kidney disease (4 papers, 2020 to 2024). "(2015) has demonstrated that SOD3−/− mice are more susceptible to renal injury in an Adriamycin-(ADR)-induced nephropathy model." (PMID 33805942, 2021). "Patient characteristics, including sex, age, body mass index (BMI), etiology of primary renal disease, basic monthly biochemical data, ROS, SOD3, IL-2, IL-6, and IL-18, were analyzed." (PMID 35740095, 2022). "Blood samples from all participants were collected for ROS, SOD3, IL-2, IL-6, and IL-18 measurement at the beginning of the study, and every kidney disease-related admission or death was recorded for the next year." (PMID 35740095, 2022). "The results showed that plasma SOD3 and serum IL-18 were two strong predictors of the first kidney disease-related hospitalization or death." (PMID 35740095, 2022). "This study aims to test the correlations between ROS, SOD3, IL-2, IL-6, and IL-18 and the first kidney disease-related hospitalization or death events in ESRD patients undergoing regular hemodialysis." (PMID 35740095, 2022). "SOD3−/− mice have recently been used to study the contribution of oxidative stress to proteinuric kidney diseases." (PMID 33805942, 2021). "In this study, plasma SOD3 and IL-18 levels were significantly correlated with the onset of first kidney disease-related hospitalization or death and could be applied as novel predictors in clinical practice." (PMID 35740095, 2022).
neurodegenerative disease (3 papers, 2019 to 2022). A disorder of the central nervous system characterized by gradual and progressive loss of neural tissue and neurologic function. "Thus, it seems that proper affinity of SOD3 to the ECM is essential for the prevention of inflammatory and degenerative diseases in the cardiovascular system." (PMID 32004354, 2020).
benign tumors (2 papers, 2016 to 2024). "However, in some benign tumors, SOD3 is positively correlated, and in mouse embryonic fibroblast cells, high levels of the enzyme promote cell growth and transformation." (PMID 39589950, 2024).
immune diseases (2 papers, 2021). "It has been reported that SOD3 exerts anti-inflammatory abilities in several immune disorders." (PMID 34208517, 2021).
metabolic disease (2 papers, 2021 to 2024). A congenital disorder (due to inherited enzyme abnormality) or acquired (due to failure of a metabolically important organ) disorder resulting from an abnormal metabolic process. "ROS and redox enzymes, such as SOD3, are involved in a variety of cellular phenomena ranging from DNA damage and point mutations to tissue-level metabolic disorders." (PMID 38247543, 2024).
muscular disorders (1 paper, 2024). "SOD3 positively correlated genes are primarily associated with cardiovascular and muscular disorders." (PMID 39480826, 2024).
neurological diseases (1 paper, 2025). "Both gst‐44 and sod‐3 are associated with neurological diseases." (PMID 41404534, 2025).
SOD3 also shares sentences with these, for which no sentence is quoted: adenocarcinoma (3 papers); osteoarthritis (3); cardiac hypertrophy (2); chronic heart failure (2); hepatocellular carcinoma (2); pneumonia (2); retinopathy (2); -amyloid (1); abortion (1); acute kidney injury (1); acute myocardial infarction (1); acute respiratory distress syndrome (1); allergic asthma (1); amyotrophic lateral sclerosis (1); angina pectoris (1); Anxiety (1); arteriosclerosis (1); asbestosis (1); bacterial infections (1); brain injury (1); Carbohydrate Metabolism Disorders (1); cervical cancer (1); chronic lung disease (1); end-stage renal disease (1); escherichia coli infection (1); essential hypertension (1); Friedreich ataxia (1); gout (1); Hearing impairment (1); Hyperkeratosis (1).
A further 33 diseases each share a sentence with SOD3 in 1 paper.